H19 (H19 imprinted maternally expressed transcript)
Diseases named in the same sentence as H19 in open-access papers (continued):
Sharing a sentence is not in itself a finding about the gene and the disease.
endometriosis (continued). "Currently, the mechanistic underpinnings for how H19 regulates downstream molecules to control glucose metabolism in endometriosis stromal cells is unclear." (PMID 38744310, 2024). "The reported studies suggest significant roles of VEGF, IGF and H19 expression in the pathogenesis of endometriosis." (PMID 38791310, 2024). "Studies have shown that H19 expression is noticeably higher in the ectopic endometrium of patients with endometriosis than in the normal endometrium." (PMID 37507391, 2023). "H19 usually is abundantly expressed in late-proliferating ESCs, whereas in the situ endometrium of endometriosis, its expression is downregulated." (PMID 37455911, 2023). "Studies have revealed that the in situ endometrium of endometriosis exhibits a marked reduction in H19 expression." (PMID 37455911, 2023). "Recent literature data suggest that the following lncRNAs are associated with endometriosis: UCA1, MALAT1, TC0101441, and H19." (PMID 36232884, 2022). "This study aimed to analyze the level of expression of four long non-coding RNA (UCA1, MALAT1, TC0101441, and H19) in endometriosis." (PMID 36232884, 2022). "The expression of the H19 gene in endometriosis patients was statistically significantly lower than in the control group." (PMID 36232884, 2022). "Statistically, there was a significantly lower expression of H19 in cases of endometriosis compared to controls." (PMID 36232884, 2022). "Imprinted long noncoding RNA H19 (lncRNA H19) has been suggested to be involved in pathogenesis of endometriosis via regulation of cellular proliferation and differentiation." (PMID 35459174, 2022). "Multivariate logistic regression analysis showed that H19 overexpression in endometriosis lesions is a prognostic factor for endometriosis recurrence." (PMID 36232884, 2022). "Expression of H19 was decreased in eutopic and ectopic endometrial lesions of endometriosis group, in comparison with the control group." (PMID 35459174, 2022). "Findings of this study showed that VEGF, IGF1, IGF2 and H19 lncRNA genes expression and epigenetic alterations of H19 lncRNA have dynamic role in the pathogenesis of endometriosis." (PMID 35459174, 2022). "The only lncRNA in which our statistical analysis showed a significant correlation with endometriosis was H19." (PMID 36232884, 2022). "But a few studies exhibited that lncRNA H19 expression in the ectopic and eutopic endometrial tissues of endometriosis was significantly higher than the normal endometrium." (PMID 35459174, 2022). "There are studies showing that the expression of H19 lncRNA in the ectopic and eutopic endometrial tissues of endometriosis is much higher than in normal endometrial tissues." (PMID 36232884, 2022). "H19 has been shown to regulate several pathways that are important in endometriosis, IGF1R, ITGB3, IER3, and ACTA2." (PMID 36232884, 2022). "Our findings represent the first example of a function of lncRNA H19 in endometriosis in vivo and thus have implications for the pathogenesis and treatment of endometriosis." (PMID 33656053, 2021). "In the eutopic endometrium of patients with endometriosis, downregulation of H19 will increase let-7 activity, contributing to a reduction in the proliferation of endometrial stromal cells through Igfr1 expression inhibition." (PMID 34638843, 2021). "In a female nude mice model, knockdown of H19 in ectopic endometrial stromal cells (ecESCs) suppressed endometriosis in vivo." (PMID 34638843, 2021). "The long noncoding RNA (lncRNA) H19 is involved in the pathogenesis of endometriosis by modulating the proliferation and invasion of ectopic endometrial cells in vitro, but related in vivo studies are rare." (PMID 33656053, 2021). "Previous studies have shown that the expression of H19 was significantly decreased in women with unexplained infertility, spontaneous abortion, endometriosis as well as RIF." (PMID 34243770, 2021).
endometriosis (continued). "The results suggested that downregulation of lncRNA H19 inhibited the tumorigenicity of ecESCs in subcutaneous implants in nude mice, and knockdown of lncRNA H19 suppressed endometriosis in vivo." (PMID 33656053, 2021). "They found that H19 expression in the both the ectopic and eutopic endometrium of endometriosis patients was significantly higher than in the normal endometrium." (PMID 34768856, 2021). "Further multivariate logistic regression analysis showed that H19 overexpression in endometriosis lesions is a prognostic factor for endometriosis recurrence." (PMID 34768856, 2021). "In this study LncRNA H19 expression in the ectopic and eutopic endometria of endometriosis patients was significantly higher than that in the normal endometrium." (PMID 34638893, 2021). "Our prior study indicated that in the ectopic endometrium of women with endometriosis, downregulation of lncRNA H19 inhibits the proliferative and invasive abilities of stromal cells through modulation of miR-124-3p and ITGB3 expression." (PMID 33656053, 2021). "H19 has been shown regulate several pathways that are relevant in endometriosis including IGF1R, ITGB3, IER3, and ACTA2." (PMID 34768856, 2021). "In our prior study, we analyzed the endometrial transcriptome in patients with endometriosis using RNA sequencing technology and found that lncRNA H19 had the highest upregulation in both ectopic and eutopic endometrium." (PMID 33656053, 2021). "In vivo experiments strongly indicated a suppression effect of H19 over-expression on Th17 differentiation and it inhibition on the growth of endometriosis-like lesions." (PMID 31636893, 2019). "In endometriosis, the upregulation of H19 expression was shown to promote endometriotic stromal cell proliferation through the downregulation of let-7 to target IGF1R." (PMID 29116025, 2017). "Endometriosis patients have decreased H19 expression at the level of eutopic endometrium, which leads to increased let-7 bioavailability." (PMID 26089099, 2015). "Here we report that H19 expression is significantly decreased in the eutopic endometrium of women with endometriosis as compared to normal controls." (PMID 26089099, 2015). "In this report, we show that the expression of both H19 and Igf1r is significantly decreased in the eutopic endometrium of women with endometriosis." (PMID 26089099, 2015). "Our results show that women with endometriosis have decreased H19 expression as well as a concomitant decrease in the level of Igf1r mRNA in the eutopic endometrium compared to women without endometriosis." (PMID 26089099, 2015). "In endometriosis, estrogen favored H19-mediated invasion of eutopic endometrial stromal cells." (PMID 40885718, 2025). "Besides conventional protein coding RNAs, non-coding RNAs, including lncRNAs such as H19, AC002454.1, LINC01279, and FAS-AS1, have been implicated in the pathophysiology of endometriosis." (PMID 40457415, 2025). "The coordinated action of VEGF, IGF1/2 and H19 factors influences the development of endometriosis." (PMID 38791310, 2024). "Additionally, estrogen-induced alterations in stromal cell invasion and migration in endometriosis are mediated by the H19/miR-216a-5p/ACTA2 axis." (PMID 38166752, 2024). "Our study provides a functional link between H19 expression and histone lactylation and glucose metabolism in endometriosis, providing new insights into disease mechanisms that could result in novel therapeutic approaches." (PMID 38744310, 2024). "17β-estradiol is therefore involved in the development of endometriosis by regulating H19." (PMID 38791310, 2024). "H19 regulates endometrial tissue proliferation by altering IGF signaling in endometriosis." (PMID 38791310, 2024). "In women with endometriosis, ectopic endometrial cells have an increasing level of H19." (PMID 38166752, 2024). "This led us to examine if the high expression of H19 in endometriosis could alter the level of aerobic glycolysis." (PMID 38744310, 2024).
endometriosis (continued). "Elevated levels of VEGF expressioncorrelate with decreasedlevels of IGF1 and H19 in endometriosis." (PMID 38791310, 2024). "Nevertheless, the mechanism by which H19 increases levels of aerobic glycolysis and histone lactylation in endometriosis remains unknown and should be elucidated by future investigations." (PMID 38744310, 2024). "In other studies, endometriosis was prevented in naked mice by downregulating the H19 gene." (PMID 37507391, 2023). "This review summarizes the role of lncRNA H19 in infertility and its implication in the mechanisms of infertility from diverse causes, such as PCOS, DOR, endometriosis, UFs, ART-related pathology, and infertility caused by male-related variables, for the first time." (PMID 37507391, 2023). "H19 is a new prospective predictor of endometriosis recurrence and may be involved in the pathophysiology of endometriosis by influencing the proliferation and invasion of ectopic endometrial cells, particularly in the recurrence mechanism." (PMID 37507391, 2023). "Infertile patients displayed more evident H19 overexpression in both ectopic and eutopic endometria, implying that H19 may play a role in the incidence and progression of infertility in endometriosis." (PMID 37507391, 2023). "Some studies have also found that the mechanism of endometriosis recurrence may be related to the overexpression of LncRNA H19." (PMID 36708425, 2023). "Research suggests that H19 expression plays an important role in the pathogenesis of endometriosis." (PMID 36232884, 2022). "In the case of endometriosis tissues and/or cells, both up- and downregulated H19 were observed." (PMID 36232884, 2022). "Decreased H19 expression in endometriosis lesions probably decreased IGF1 and IGF2 expression." (PMID 35459174, 2022). "Further studies of H19 expression in endometriosis showed that expression could be differentiated in endometriosis." (PMID 36232884, 2022). "A study of 104 ectopic endometrial samples from endometriosis patients and 50 normal endometrium samples from controls revealed that the expression of lncRNA H19 in the ectopic endometrium of patients with endometriosis was significantly higher than that in the normal endometrium." (PMID 35281615, 2022). "Our study is the first to demonstrate the function of lncRNA H19 in endometriosis in vivo." (PMID 33656053, 2021). "This study aimed to investigate the role of lncRNA H19 in a nude mouse model of endometriosis." (PMID 33656053, 2021). "Based on our findings and existing literature about the role of H19 in endometriosis, we hypothesize that H19 may mediate the process of invasion and migration in endometriosis, although further studies of H19 in endometriosis are still needed." (PMID 33584822, 2021). "In conclusion, our study provided a global view of ceRNA crosstalk between mRNAs and lncRNAs in ovarian endometriosis, and identified three functional lncRNAs, H19, GS1-358P8.4, and RP11-96D1.10 that are strongly associated with the development of endometriosis." (PMID 33584822, 2021). "Besides, LncRNA H19 over-expression suppressed the growth of Th17 cell differentiation-induced endometriosis-like lesions." (PMID 31636893, 2019). "It has been shown that H19, reducing the bioavailability of miRNA let-7, by acting as a molecular sponge, was significantly down-regulated in the eutopic endometrium of women with endometriosis." (PMID 30037059, 2018). "Notably, women with unexplained infertility and women with endometriosis show decreased H19 expression in eutopic endometrium suggesting a direct clinical link." (PMID 28704412, 2017). "Alterations in this H19/Let-7/IGF1R-mediated regulation of endometrial cell proliferation may represent a potential mechanism for infertility in women with endometriosis." (PMID 26089099, 2015).
endometriosis (continued). "Normal eutopic endometrium grows quickly during the proliferative phase of the menstrual cycle, but our findings suggest that alterations of the H19/Let-7/IGF1R pathway may impair eutopic endometrial cell growth in women with endometriosis." (PMID 26089099, 2015). "Given the concomitant downregulation of H19 and Igf1r in the eutopic endometrium of endometriosis (Fig1A and B), we sought to determine whether H19, through sequestering let-7, might regulate Igf1r expression in the human endometrial stromal cells." (PMID 26089099, 2015). "Thus, H19 knockdown and overexpression experiments were performed in endometrial stromal cells derived from four patients with endometriosis." (PMID 26089099, 2015). "Together, these results suggested that decreased expression of H19 and Igf1r might contribute to impaired development and function of eutopic endometrium in patients with endometriosis." (PMID 26089099, 2015). "Taken together, these data demonstrate elevated expression levels of H19 in endometriosis patients promote abnormal glucose metabolism and elevated histone lactylation levels in vivo, enhancing cell proliferation and migration and promoting the progression of endometriosis." (PMID 38744310, 2024). "Alterations in the H19/miR-216a-5p/actin alpha 2 (ACTA2) pathway may be involved in H19-mediated invasion and migration of ectopic ESCs, which could be an underlying cause of fibrogenesis or fibrosis in patients with endometriosis." (PMID 37507391, 2023). "It has also been suggested that the overexpression of lncRNA H19 was an independent prognostic factor and the level of lncRNA H19 can predict recurrence through sensitivity and specificity, implying that lncRNA H19 can be used as a predictor of endometriosis recurrence." (PMID 35281615, 2022). "In addition, H19 levels correlated with the clinical degree (staging) of endometriosis." (PMID 36232884, 2022). "Additionally, hypomethylation of H19-DMR region II may be involved in impaired IGF2 regulation in endometriosis." (PMID 35459174, 2022). "Our study may shed further light on the role of H19 in the development of endometriosis." (PMID 33584822, 2021). "However, there are few studies on the role of lncRNA H19 in endometriosis." (PMID 33656053, 2021). "In our study, we have shownthat the expression of both H19 and IGF1 is significantly reduced in women with endometriosis." (PMID 38791310, 2024). "Next, we verified the expression of H19 in normal mouse endometrium (UC) and the eutopic endometrium (UE) and ectopic tissue (ENDO) obtained from the endometriosis model using RT-qPCR." (PMID 38744310, 2024). "As a result of activation of the H19/miR-216a-5p/ACTA2 pathway, the formation of fibrotic tissue is stimulated in patients with endometriosis." (PMID 38791310, 2024). "It was noted that the expression profiles of the H19, IGF1 and IGF2 genes werereduced in eutopic and ectopic endometrial tissues of patients with endometriosis compared to control tissues." (PMID 38791310, 2024). "Genes expression profile of H19, IGF1 and IGF2 was decreased in eutopic and ectopic endometrial tissues of endometriosis group, compared to the control tissues." (PMID 35459174, 2022). "The results showed that expression of H19, IGF1 and IGF2 genes was decreased in eutopic and ectopic endometrial tissues of endometriosis group in comparison with control group." (PMID 35459174, 2022). "Another study showed that alterations in the lncRNA H19/miR-216a-5p/ACTA2 pathway affect the invasion and migration of eutopic endometrial stromal cells and contribute to fibrosis in women with endometriosis." (PMID 34638843, 2021). "We observed the weight of endometriosis-like lesions from nude mouse endometriosis model was increased in EMS + Th17 group, and H19 over-expression decreased the weight of endometriosis-like lesions compare to EMS + Lenti-NC-Th17 group." (PMID 31636893, 2019).
endometriosis (continued). "The overlapping among lncRNAs involved in EC and Endometriosis showed that MALAT1 and H19 are shared across the two pathologies, even if, they show a different trend of expression." (PMID 30037059, 2018). "H19 levels were elevated in both UE and ENDO in the endometriosis model compared to UC." (PMID 38744310, 2024). "By interfering with the H19/Let-7/IGF1R regulation system, endometriosis patients may experience spontaneous miscarriage or infertility due to diminished endometrial readiness and pregnancy receptivity." (PMID 37455911, 2023). "Disruption of the H19/Let-7/IGF1R regulatory pathway may contribute to impaired endometrial preparation and receptivity in women with endometriosis." (PMID 36232884, 2022). "Therefore, in our study, decreased H19 expression probably reduces expression of IGF1 and thus decreased IGF1 signaling, leading to reduced stromal cell proliferation rate in endometriosis patients." (PMID 35459174, 2022). "In the present study, we evaluated and compared expression levels of H19 RNA factor and angiogenic (VEGF) and proliferative (IGF1, IGF2) genes in endometrium of non-endometriosis women in comparison with eutopic and ectopic tissues of endometriosis women." (PMID 35459174, 2022). "Similarly, the inhibition of miR-342-3p regulated by lncRNA H19 reduced the percentage of T17 cells/CD4+ and T cells and inhibited endometrial stromal cell viability to relieve endometriosis." (PMID 34055578, 2021). "Another study showed that alterations in the lncRNA H19/miR-216a-5p/ACTA2 pathway affect the invasion and migration of eutopic endometrial stromal cells and contribute to fibrous tissue formation or fibrosis in women with endometriosis." (PMID 33656053, 2021). "We did not observe a statistically significant difference in H19 expression in the cultured endometrial stromal cells from women with and without endometriosis (data not shown)." (PMID 26089099, 2015). "This was inconsistent with our in vivo data demonstrating significantly lower H19 expression in women with endometriosis as compared to woman without endometriosis (Fig1A)." (PMID 26089099, 2015). "Perturbation of this newly identified H19/Let-7/IGF1R regulatory pathway may contribute to impaired endometrial preparation and receptivity in women with endometriosis." (PMID 26089099, 2015). "Mann–Whitney’s U-test revealed a significant H19 decrease in the endometriosis (Endo) compared to the nonendometriosis (Ctl) group (medians of Endo and Ctl were 1.96 and 8.10, respectively; P = 0.035, Fig1A)." (PMID 26089099, 2015). "We propose that perturbation of this newly identified H19/Let-7/IGF1R regulatory pathway may contribute to impaired endometrial preparation and receptivity for pregnancy in women with endometriosis." (PMID 26089099, 2015). "Due to the fact that women with unexplained infertility show reduced expression of H19 in the eutopic endometrium, H19 regulates let-7 and let-7 targets IGF1R, and it is useful to determine the role of H19 in the endometrium and its relationship to IGF signaling in endometriosis." (PMID 38791310, 2024). "The present study was designed to elucidate VEGF, IGF1, IGF2 and H19 lncRNA genes expression and epigenetic alterations of differentially methylated region (DMR) of H19 (H19-DMR) regulatory region in endometrial tissues of patients with endometriosis, in comparison with control women." (PMID 35459174, 2022). "To determine whether reduced IGF2 and H19 gene expressions in endometriosis was because of epigenetic modifications or not, we then analyzed epigenetic alterations of the H19-DMR regulatory regions." (PMID 35459174, 2022).